IFNG (interferon gamma)
Diseases named in the same sentence as IFNG in open-access papers (continued):
Sharing a sentence is not in itself a finding about the gene and the disease.
infection (continued). "However, mice lacking CCR6 showed an increased frequency of IFNγ-producing CD8 cells already on d 3 of infection, indicating a lower activation threshold or the absence of regulatory mechanisms in B6.CCR6−/− mice." (PMID 23028548, 2012). "Also, the massive expression of IFNγ in control mice late after infection did not contain viral replication in the liver and likely rather contributed to liver pathology." (PMID 21949840, 2011). "Moreover, prior infection of the macrophages with C. pneumoniae did not alter the ability of IFNγ to induce IRF-1 in BMDM of both genotypes." (PMID 22096480, 2011). "There was no IFNγ detected from CD11b+ DCs or monocytes despite low levels of infection." (PMID 21559416, 2011). "Thus, the M2 ISRE functions as a repressor of MHV68 replication at late times of acute infection, and acts by a mechanism that seems to require functional IFNαβ, but not IFNγ, signaling." (PMID 22114555, 2011). "Compared to sera from unchallenged control mice, serum levels of IFNγ (mean 7–21-fold increase), IL-6 (20–40-fold increase), and IL-17 (mean 8–12—fold increase) levels were significantly raised in immunized, but not un-immunized mice on day 2 of infection." (PMID 20967278, 2010). "Taken together, we show here for the first time that the IFNγ-induced endogenous Irgm1 localises to the late endocytic/lysosomal (LAMP1-positive) compartments in addition to the Golgi apparatus in the absence of infection." (PMID 20072621, 2010). "As opposed to IFNγ and IL-6, the production of IL-17A could not be further induced by infection doses beyond 10×LD50." (PMID 20585449, 2010). "As expected, a classical Th2 cytokine profile with up-regulation of IL-5, IL-13 and to a lesser extent of IL-4, but with no changes in IFNγ transcript levels, was observed in these pooled samples with expression levels peaking after the third immunising infection and immediately after challenge." (PMID 20950493, 2010). "In fact, multiple studies provide evidence that IFNγ-producing CD8+ T cells persist during neuronal latency in areas of T cell infiltration, suggesting persistent antigen stimulation and T cell activation during latency despite a failure to clear the infection." (PMID 21994578, 2009). "However, significant reduction in the production of TNF, IFNγ, and IL10 were observed in SR-B1−/− mice following infection with a high dose of Mtb (1000 CFU/mouse), which marginally affected the size of inflammatory foci but did not influence bacterial burdens." (PMID 20041149, 2009). "Also, the evidence that interferon-gamma helps prevent serious infection in CGD does not warrant its use in all patients." (PMID 19381301, 2009). "Indeed, transcripts of STAT-1, a key actor of this pathway, were drastically down-regulated at 24 h after infection, though there is no external activation by IFNγ." (PMID 18495030, 2008). "However, despite iNKT cell IFNγ and TNF production, and enhanced NK cell IFNγ production in the liver following α-GalCer administration during infection, the control of L. donovani was not improved." (PMID 18463695, 2008). "Additionally, using myr1 knockout parasites that fail to export dense-granule effectors, we observed no change in IFNγ or in IFNγ produced by CD3+ Vγ9+ cells compared with parental infections, indicating that MYR1-dependent export is not required for early activation." (PMID 41452934, 2025). "In addition, the cytokine profile of the hypervirulent isolates in A/J mice had a profound IFNγ and IL-17 response, and lung resident CD4 T-cells isolated from A/J mice expressed significantly increased Th1 (CXCR3, Tbet) and Th17 (RORγT) markers compared with KN99α infection." (PMID 40029251, 2025). "Moreover, when co-inoculation of anti-Acr IgA TBA61 mAb and mouse IFNγ via i.n. route in Balb/c mice with IL-4 depletion by a neutralizing anti-IL4 mAb, a significant reduction of bacterial burdens can be observed compared with IgA and IFNγ treatment in wild-type mice after H37Rv infection." (PMID 41200176, 2025).
infection (continued). "In addition, because Chlamydia is likely not exposed to IFNγ during a primary infection in epithelial cells until they have already established their inclusion niche and are actively replicating, we treated cultures at 24 hours post-infection (hpi) to better model this situation." (PMID 39194253, 2024). "Importantly, basal JAK2 and STAT1 transcript and protein levels were dampened by infection even in the absence of interferon, which could have implications for cytokine signaling beyond IFNγ." (PMID 39194253, 2024). "Thus far, only case reports have described attempted treatment with IFNγ supplementation, rituximab, or cyclophosphamide combined with prednisone in patients with anti-IFNγ auto-antibodies and a double infection with TB and NTM with both positive and negative outcomes." (PMID 38203686, 2023). "However, in the context of infection by F. tularensis, Sts-/- BM-derived monocytes, but not BMDMs or BMDCs, demonstrated heightened bactericidal activity that was accompanied by enhanced IFNγ signaling." (PMID 37240179, 2023). "However, IST can only prevent clearance in cells that have not been pre-stimulated with IFNγ, a condition that may only be met in the early stages of infection." (PMID 37459303, 2023). "Furthermore, we found that IFNγ may be dispensable to this process and despite the BM adaptation to infection, the generated monocytes or macrophages do not acquire an improved capacity to respond to secondary challenges." (PMID 37383236, 2023). "Interestingly, 4 proteins (IFNγ, IL9, IP10, and MIP1α) overlapped between the two identified signatures, suggesting differential expression of these is associated with active TB disease, rather than infection per se." (PMID 35401549, 2022). "In addition, when we examined the antigen-nonspecific CD8+ T cell response, interferon-gamma positive (IFN-γ+) CD8+ T cells were increased in intravenously inoculated CMs and in CMs preadministered an anti-CD8 MAb after the inoculation of cells compared to the levels before infection." (PMID 36314828, 2022). "In vitro IL-2, IFNγ and IP-10 responses to C. burnetii were significantly elevated in exposed compared to unexposed participants, regardless of whether exposure occurred through infection or vaccination." (PMID 35812430, 2022). "Additionally, our pathway analysis revealed seven genes, IL-4, IFNγ, TLR4, CXCL8, IL-18, CSF2 and TNFα, are involved in the morphological and behavioral changes of macrophages, monocytes, granulocytes, and dendritic cells (DCs) and their recruitment into infection sites." (PMID 34753991, 2021). "Similarly, mice with neutralized IFNγ did not exhibit increased viral loads in the liver or spleen nor increased liver enzymes compared to isotype-treated mice just one day prior to succumbing to the infection." (PMID 33572859, 2021). "Interestingly, when the plasma IFNγ levels were measured in all of the experimental groups at the peak stage of the infection (Tp), both non-vaccinated mice as well as DTPa-vaccinated mice exhibited increased circulating cytokine levels, with the latter being significantly higher." (PMID 34200074, 2021). "Additionally, CD27 expression was noted in a subset of IFNγ producing γδ T-cells following infection, while CD27 negative γδ T-cells did not produce IFNγ, suggesting a role for CD27 in regulation of interferon and specific cytokine production in immune responses." (PMID 34630390, 2021). "In addition, compared with B6 mice, Lm-infected B6.Il18−/−, B6.Nlrp3−/−, and B6.Batf3−/− mice showed reduced levels of serum IFNγ without any effect on the bacterial burden at 24 h post-infection, demonstrating that these factors also regulate IFNγ production during Lm infection." (PMID 35053151, 2021). "Furthermore, the addition of IFNγ resulted in improved control of parasite growth in both Il27ra-/- and WT macrophages, while the addition of IL-27 had no significant impact on the establishment of infection or growth of parasites in WT macrophages." (PMID 33049000, 2020).
infection (continued). "To evaluate whether the infection of bovine BMDMs is underpinned by distinct parasite expression signatures, we used the RNA-sequencing reads uniquely aligning to the parasite genome (GT1 v.46) to evaluate stochastic changes in Toxoplasma transcript abundance in naïve and IFNγ-stimulated BMDMs." (PMID 33014886, 2020). "Thus, it can be hypothesized that increased Tbet expression observed in the mice treated before infection may be responsible for the lack of a decrease in IFNγ observed in this group." (PMID 32033605, 2020). "Because HTLV-1 promotes the production of cytokines such as interferon-gamma, tumour necrosis factor-alpha, and interleukin-6, through the activation of nuclear factor-κB and cyclic AMP response element-binding protein, inflammatory factors might be induced even during asymptomatic infection." (PMID 32706758, 2020). "However, unlike IL-21, CD4 T cell-derived IFNγ may act by primarily promoting CD8 T cell entry into the site of infection." (PMID 31514273, 2019). "On the other hand, it could be that such protection from reactivation of lymphatic LTBI could be mediated by activated macrophages, which were shown to be more abundant in another model of reactivation from latent-like infection upon corticosteroid treatment, as opposed to IFNγ+ T cells." (PMID 30949177, 2019). "Therefore, we asked whether Mtb impaired MHC class I expression in our in vitro infection system, especially since the TGPMs were not pre-activated with IFNγ prior to infection." (PMID 29782535, 2018). "We found that the percentage of CD4+ T cells producing IFNγ and TNFα were significantly reduced in the groups receiving ART plus PH-797804 compared to ART alone, whether the treatment is started on week 1 (p = 0.005 for TNFα and p = 0.02 for IFNγ) or week 6 post-infection (p = 0.04 for TNFα)." (PMID 30161247, 2018). "Indeed, the complex M1 milieu was not affected by GM-CSF neutralization, with no M1/M2 switch, indicating that the main pathway inducing M1 macrophage polarization after M. tuberculosis in vivo infection is not GM-CSF-dependent but most likely IFNγ produced by Th1, NK or NKT cells." (PMID 29872095, 2018). "Interestingly, although slightly higher amounts of IFNγ could be found in LTβR−/− compared to WT animals before infection, these amounts did not increase after infection, as seen in WT animals, where levels rose about 4-fold." (PMID 28845089, 2017). "Contrary to our prediction and unlike Ms/Ec infection, birinapant could neither influence Ld-induced NO levels over Ld control nor assisted IFNγ for boosting NO level over IFNγ control, indicating its redundancy for affording immunity in the macrophages infected with pathogenic microbes." (PMID 29375545, 2017). "Our data suggest that, strong IFNG/IL22 responses, probably related to Th1 and NK cell involvement, is important for clearance of C. trachomatis and that the residual pro-inflammatory and pro-fibrotic phenotype that persists after infection might contribute to pathological scarring." (PMID 28966918, 2017). "Interestingly, whilst IFNG was strongly upregulated in individuals with C. trachomatis infection, there was much less upregulation in individuals with disease but not infection, suggesting that the IFNG response is quickly down-regulated once C. trachomatis has been cleared." (PMID 28966918, 2017). "Similarly, the infection of primary bone-marrow derived macrophages revealed no phenotypic difference between mutant and wild type bacterial strains, even following macrophage activation with IFNγ." (PMID 25822753, 2015). "Lower MA-EBOV viremia levels were observed in the 24 hour post challenge treated mice, but not in the 24 hour pre-infection treatment group, suggesting that IFNγ administration as a post-exposure antiviral may prove more efficacious than when used prophylactically." (PMID 26562011, 2015).
infection (continued). "However, activated IFNγ–/– CD8+ T cells harboring transgenic T-cell receptors (TCRs), which can recognize specific cognate epitopes presented on the surface of infected hepatocytes, are still capable of controlling infection as their IFNγ-proficient counterparts." (PMID 25699034, 2015). "Interestingly, unlike EBOV, BDBV, and MARV infection, infection with SUDV did not result in increased expression of IFNγ, suggesting that filovirus species may differentially modulate type II interferon expression." (PMID 26512687, 2015). "This difference may not be solely attributed to the genetic background of the mice as Itk−/− on a BALB/c background have also been reported to significantly reduce IL-4 production in the absence of a significant effect on IFNγ, however this was following infection with L.major." (PMID 25250764, 2014). "Interestingly, TNFα is absolutely required at the time of challenge infection and can be provided by either T cells or non-T cells, whereas IFNγ provided by T cells prior to challenge appears to facilitate the differentiation of optimally protective CD8 T cells." (PMID 24854422, 2014). "Thus using DC2.4 and the same infection protocol, global VACV epitope presentation was probed up to 12 hpi using splenocytes taken from mice seven days after VACV infection and the percent of CD8+ T cells making IFNγ determined by intracellular cytokine staining (ICS)." (PMID 23382674, 2013). "Interestingly, RIG-I only played a minor role in the cellular response to this pathogen in the absence of IFNγ, suggesting that the IFNγ response ensures the recognition of the infection through an immunosurveillance pathway that is otherwise dispensable for controlling S. flexneri growth." (PMID 22912573, 2012). "Increasing the inflammatory response by exogenous administration of IFNγ, PolyI:C or CpG did not affect memory conversion in the late transferred group, suggesting that the diverging antigen load early versus later during acute infection had determined their fate." (PMID 21253594, 2011). "Although T cell interferon-gamma release-assays (IGRA) are a major advance in diagnosis of LTBI, reliance on IFN-γ as the sole read-out means they provide only limited biological information which is clinically interpreted in a binary fashion, indicating either presence or absence of infection." (PMID 21179481, 2010). "IFNγ secretion was not different between FPPS knockout and wild-type infection, arguing against an important role for parasite-derived HMBPP." (PMID 40667022, 2025). "Among the polymorphisms associated in one cohort which were tested in different cohorts but where the association was not replicated, we have IL18 rs2043055 with CCC, IFNG rs2430561 and infection, IL4 −590 and infection, TGFB1 −509 rs1800469 and infection." (PMID 40297326, 2025). "However, as the disease progresses to a chronic active disease (G2), infection loads climb and there is a shift in the Th2 systemic response only, marked by moderate increases in systemic anti-Chlamydia IgG with no change in Th1 responses (measured by IFNγ related pathways)." (PMID 39600869, 2024). "While not significant, we observed increased IFNγ production by central memory T-cells in group NL4.3 in both CD4 and CD8 T-cells following the boost immunization but prior to infection (W11)." (PMID 38675751, 2024). "MHV68 infection drives the increase in the ABC population; however, the role of STAT1 and IFNγ signaling in MHV68-driven ABC expansion has not been tested." (PMID 39440973, 2024). "Pioneering mouse studies found a role for IL-12 in the early coordination of innate immunity upon infection, but IL-12 signals did not impact the ability of IAV-primed CD4 T cells to produce IFNγ." (PMID 38607077, 2024). "Women who spontaneously cleared infection without treatment exhibited increased CT-specific IFNγ+ CD4 T cells and were less likely to be reinfected when compared to women who required antibiotics for infection resolution." (PMID 39043447, 2024).
infection (continued). "In mice epithelial cells, however, IFNγ induces expression of p47 GTPases, but not IDO, demonstrating host infection tropism and defining an important difference to consider when utilizing mouse models of chlamydia infection." (PMID 39203989, 2024). "Within the lung tissue, there were no increases in the numbers of Ifnγ+ CD4 and CD8 T cells 5 days after infection." (PMID 37842651, 2023). "We show that, unlike IFNγ+ T cells, AIM+ virus-specific CD4+ and CD8+ TSCM are more adequate markers of T cell memory, even beyond 18 months post-infection." (PMID 37046496, 2023). "Human immunodeficiency virus (HIV) and the closely related simian immunodeficiency virus (SIV) both induce STAT1 phosphorylation, where it plays a role in maintaining the infection, and in the case of HIV, it was independent of IFNγ." (PMID 37655893, 2023). "Ly6A/E expression was not impacted by anti-IFNγ treatment, but BST2 was significantly reduced, albeit modestly, in AT2 and CD24 + EC, the two major cell types that are targeted for infection by SARS-CoV-2." (PMID 38086794, 2023). "After infection with SARS-CoV-2, cells from patients with AUD had a robust inflammatory response, including higher levels of TNFα, IL-1β, and IFNγ secreted than infected non-AUD cells." (PMID 37786945, 2023). "For example, the CD8 T cell IFNγ response to SF46 is quite low, unlike the high IFNγ level elicited in response to SF20 infections." (PMID 37287466, 2023). "However, the question remains why IFNγ failed to enhance downstream IP-10 secretion in the cluster 2 indviduals with adaptive responses to C. burnetii, and what implications this might have for their protection from C. burnetii (re-)infection." (PMID 35812430, 2022). "IL-10 and IFNγ CD4+ cells are important for a chronic, nonresolving infection status, and together with the elevated TNFα and IL-6 expression, these data fit well with the enhanced and prolonged inflammation in the colons of AOM/DSS-treated CerS4 LCK/Cre mice." (PMID 35163788, 2022). "Expression of Notch1 on IFNγ+CD4+T cells revealed an increase between days 7 and 14 of infection in lungs but not LNs." (PMID 35603470, 2022). "By day 17 post infection, P25TCR-Tg but not endogenous, IFNγ-producing T cells were significantly more abundant in mice infected with 4334 than H37Rv." (PMID 35695454, 2022). "Ectopic synthesis of itaconate in A549 cells, which do not physiologically express ACOD1, reduced infection-driven inflammation, and DI reduced IAV- and IFNγ-induced CXCL10 expression in murine macrophages independent of the presence of endogenous ACOD1." (PMID 35025971, 2022). "Cytokine levels have also a positive correlation between sex the levels of IFNγ were higher in control males, meanwhile, TNF-α and IL-6 were higher in females without infection, indicating that females have a basal proinflammatory profile." (PMID 35335632, 2022). "In contrast, decreased Fads1 expression at 6 hr post infection correlated with a marked reduction of FADS1-mediated conversion of DGLA in AA, irrespective of IFNγ stimulation." (PMID 34951591, 2021). "Overall, 6 of the animals with confirmed infection were missed by both SICCT and IFNγ tests (6/286; 2.10%), and none of these were disclosed using any of the serological antibody tests." (PMID 33848298, 2021). "The peak of IL-13, IFNγ, and TNF levels in the BALF was at day 11 or earlier in adult mice infected with P. murina but not until day 28 post-infection in mice infected as pups (Figure A3A–C)." (PMID 34682248, 2021). "The concentrations of IL-4, IL-5, TNF, and IFNγ in the BALF of BALB/c pups were also higher, though not statistically different, than in C57BL/6 pups at day 27 post-infection (Figure A2E–G)." (PMID 34682248, 2021). "We also quantified in the hiPSC-derived trophoblasts the secreted levels of type I (IFNA2), type II (IFNG) and type III (IFNL1) IFNs produced by these cells in the absence of virus or after infection with ZIKVBR and culture for 48 h or 96 h." (PMID 32745093, 2020).